RNU6-1118P (RNA, U6 small nuclear 1118, pseudogene)
Gene: Small nuclear RNA gene on chromosome 10 (38,423,625 to 38,423,728, forward strand). Ensembl gene ENSG00000222314.
Homologues: Orthologues: chimpanzee U6 (96% identical), macaque U6 (91% identical), pig U6 (84% identical), pig U6 (78% identical), dog U6 (77% identical). Paralogues in human: RNU6-1076P (100% identical), RNU6-1100P (100% identical), RNU6-1217P (100% identical), RNU6-355P (100% identical), RNU6-447P (100% identical), RNU6-785P (100% identical), RNU6-791P (100% identical), RNU6-860P (100% identical), U6 (100% identical), RNU6-1054P (99% identical), RNU6-1199P (99% identical), RNU6-1319P (99% identical), and 1289 more.